ENSG00000253065
Synonyms: LOC124900211
Gene: Small nucleolar RNA gene on chromosome 5 (168,033,091 to 168,033,205, reverse strand). Ensembl gene ENSG00000253065.
Gene Ontology:
Biological process: RNA processing
Cellular component: nucleolus
Homologues: Orthologues: mouse Gm22434 (70% identical), mouse Gm22490 (68% identical), rat Gm22598 (68% identical), mouse Gm24853 (67% identical), mouse Gm25909 (66% identical), mouse Gm22598 (63% identical), rat LOC120102737 (61% identical), rat LOC120098705 (57% identical). Paralogues in human: SNORA40B (82% identical), SNORA40 (80% identical), SNORA40C (77% identical).